KDM4D (lysine demethylase 4D)
Description:
Histone demethylase that specifically demethylates 'Lys-9' of histone H3, thereby playing a central role in histone code. Does not demethylate histone H3 'Lys-4', H3 'Lys-27', H3 'Lys-36' nor H4 'Lys-20'. Demethylates both di- and trimethylated H3 'Lys-9' residue, while it has no activity on monomethylated residues. Demethylation of Lys residue generates formaldehyde and succinate.
Synonyms: JMJD2D; FLJ10251
Tractability: Small molecule: a structure with a bound ligand is known; a high-quality ligand is known; it has a high-quality binding pocket. PROTAC: UniProt records ubiquitination sites on it; ubiquitination databases record sites on it; a small molecule that binds it is known.
Target class: Epigenetic regulator; Jumonji domain-containing; Eraser; Lysine demethylase
Chemical probes: IOX1 (high quality)
Gene: Protein-coding gene on chromosome 11 (94,973,709 to 94,999,519, forward strand). Ensembl gene ENSG00000186280.
Subcellular location: Nucleus
Subcellular location (Human Protein Atlas): Nucleoplasm
Pathways (Reactome):
Chromatin organization: HDMs demethylate histones
Gene Ontology:
Molecular function: histone H3K9 demethylase activity; histone H3K9me2/H3K9me3 demethylase activity; protein binding; histone demethylase activity; chromatin DNA binding; damaged DNA binding
Biological process: cellular response to ionizing radiation; double-strand break repair via homologous recombination; inflammatory response; positive regulation of chromatin binding; positive regulation of double-strand break repair via nonhomologous end joining; regulation of protein phosphorylation; chromatin remodeling
Cellular component: blood microparticle; nucleus; site of double-strand break; chromatin; nucleoplasm; pericentric heterochromatin
Genetic constraint (gnomAD): Loss-of-function variants: 0 observed, 0.98 expected, observed/expected ratio (o/e) 0, 90% interval 0 to 1.73. That is too few expected variants to judge how well the gene tolerates losing a copy. Missense variants: 427 observed, 695.4 expected, observed/expected ratio (o/e) 0.61, 90% interval 0.57 to 0.67. Synonymous variants: 254 observed, 259.19 expected, observed/expected ratio (o/e) 0.98, 90% interval 0.88 to 1.09.
Homologues: Orthologues: chimpanzee KDM4D (99% identical), macaque KDM4D (98% identical), guinea pig KDM4D (70% identical), mouse Kdm4d (69% identical), rat Kdm4d (68% identical), zebrafish kdm4c (49% identical), Drosophila melanogaster Kdm5 (25% identical), Caenorhabditis elegans rbr-2 (21% identical). Paralogues in human: KDM4F (68% identical), KDM4E (64% identical), KDM4B (54% identical), KDM4C (51% identical), KDM4A (49% identical), KDM5A (26% identical), KDM5B (26% identical), KDM5C (26% identical), KDM5D (26% identical), JARID2 (17% identical).
Diseases named in the same sentence as KDM4D in open-access papers:
KDM4D is named in the same sentence as 40 diseases in open-access papers, as found by Europe PMC text mining. Sharing a sentence is not in itself a finding about the gene and the disease. The quoted sentences say what the papers report.
hepatocellular carcinoma (5 papers, 2021 to 2024). A malignant tumor that arises from hepatocytes. "Moreover, the activities of H3K9me3 modifiers and readers depend on the molecular context, as shown in the case of KDM4D in ß-catenin-mutated hepatocellular carcinoma." (PMID 39519018, 2024). "In colorectal cancer and hepatocellular carcinoma, KDM4D acts as a coactivator of Wnt/β-catenin, Hedgehog, HIF1, JAK-STAT3, and Notch pathways." (PMID 39519018, 2024). "Collectively, our results suggest that JIB-04-mediated targeting of histone demethylases, such as KDM4B, KDM4D, and KDM6B, inhibits the malignancy of hepatocellular carcinoma via growth inhibition and cell cycle arrest and, in addition, affects the maintenance and viability of liver CSCs." (PMID 35887001, 2022).
liver cancer (5 papers, 2020 to 2023). An epithelial or non-epithelial malignant neoplasm that arises from the liver. "Latest research has shown that KDM4D, the last member of this family, is overexpressed in liver cancer and colon cancer." (PMID 34667158, 2021).
gastric cancer (4 papers, 2022 to 2026). A primary or metastatic malignant neoplasm involving the stomach. "Transcriptomic analysis demonstrated significant downregulation of DPP6 and DLG2, while KDM4D, USP34, and VDR were significantly upregulated in gastric cancer tissues compared with normal controls." (PMID 42195053, 2026).
Hepatic fibrosis (4 papers, 2021 to 2024). The presence of excessive fibrous connective tissue in the liver. "For example, AAV-mediated silencing of CD47, KDM4D and nestin has been used as a strategy to reduce liver fibrosis." (PMID 38267432, 2024). "JMJD2D, or KDM4D, was recently reported as a remarkable overexpressed H3K9me2/3 demethylase during HSCs activation, it epigenetically facilitates TLR4 gene transcription and thus activates TLR4/NF-kB signaling pathways, promotes HSCs activation and hepatic fibrosis progression." (PMID 33391480, 2021).
gastrointestinal stromal tumor (3 papers, 2018 to 2022). "Overexpressed KDM4D in gastrointestinal stromal tumor depended on HIF1β to promote VEGFA signaling pathway." (PMID 34820329, 2021).
leukemia (2 papers, 2017 to 2021). A malignant (clonal) hematologic disorder, involving hematopoietic stem cells and characterized by the presence of primitive or atypical myeloid or lymphoid cells in the bone marrow and the blood. "Other KDM4 family members (i.e., KDM4A, KDM4C, and KDM4D) were found to be expressed at lower and similar levels across the cytogenetic subgroups of AML including the mixed lineage leukemia gene‐associated leukemia (11q23/MLL) etc.." (PMID 34938963, 2021).
renal cell carcinoma (2 papers, 2022 to 2023). "For instance, KDM4D-IN-1 is a specific inhibitor of KDM4D with an IC50 of 0.41 μM and shows anti-proliferative and anti-angiogenic effects on renal cell carcinoma cells both in vitro and in vivo." (PMID 36975603, 2023).
Adrenocortical Cancer (1 paper, 2022). "KDM4D is related to a bad prognosis for Lung Adenocarcinoma, Adrenocortical Cancer, and Liver Hepatocellular Carcinoma." (PMID 35480330, 2022).
bladder cancer (1 paper, 2024). "The roles of KDM4 family members, including KDM4A, KDM4B, KDM4C and KDM4D, on bladder cancer remains unclear." (PMID 39461328, 2024).
breast carcinoma (1 paper, 2023). "For example, KDM4A and KDM4D are co-overexpressed in basal breast cancer, while the KDM4A level is higher in infiltrating breast duct carcinoma (IBDC) than in breast fibroadenoma, and KDM4B is overexpressed in both estrogen receptor (ER)-positive breast cancer and triple-negative breast cancer." (PMID 37692513, 2023).
diabetes (1 paper, 2022). "Except for the completely restored DEGs, Sal treatment mitigated the expression of approximately 73.08% up-regulated DEGs and 66.35% down-regulated DEGs induced by diabetes, including 8 oxidation-related genes (Aldh4a1, Acad12, Ado, Kdm4d, Acacb, Mical1, Th and Htatip2)." (PMID 35370972, 2022).
glioblastoma (1 paper, 2021). The most malignant astrocytic tumor (WHO grade IV). "Immunoblot analysis revealed that KDM4C and KDM4D protein levels were highly expressed in most of the glioblastoma cell lines, whereas the protein levels of KDM4A and KDM4B were very low or not detected." (PMID 33462212, 2021). "KDM4C and c-Myc expressions were positively correlated, whereas those of KDM4A, KDM4B, and KDM4D did not correlate with c-Myc in glioblastoma." (PMID 33462212, 2021).
kidney cancer (1 paper, 2021). Primary or metastatic malignant neoplasm involving the kidney. "To reveal the expression of KDM4D in kidney cancer tissues, we performed immunohistochemical staining on tissue microarrays of 70 ccRCC patients with complete clinical data and follow-up information." (PMID 34667158, 2021). "Next, we evaluated the role of KDM4D in angiopoiesis of kidney cancer and found that KDM4D inhibition markedly impaired neovascularization in vitro and in vivo by HUVEC tube formation assay and immumohistochemical staining of CD31." (PMID 34667158, 2021). "Furthermore, we investigate the effect of KDM4D on development and angiogenesis of kidney cancer cells in vivo." (PMID 34667158, 2021).
Obesity (1 paper, 2023). Accumulation of substantial excess body fat. "In order to verify that KDM4D is necessary to reverse obesity by dieting, we demonstrated that in vivo inhibition of KDM4D activity by pharmacological agent JIB-04 in naïve rats resulted in transcriptional repression of AgRP, decreasing orexigenic signaling, thus inhibiting hunger." (PMID 36817590, 2023). "Given that differences in post translational histone methylation of specific residues along energy-balance related genes in the ARC nucleus moderates obesity, we were interested in trying to understand the mechanism by which KDM4D acts in weight reduced rats of an obese model." (PMID 36817590, 2023). "In this research, we were interested in uncovering the molecular mechanism by which KDM4D modulates the expression of genes in the ARC after diet-induced obesity, and specifically focus on the reversal of this hypothalamic dysfunction through caloric restriction." (PMID 36817590, 2023). "To understand how the methylation status of lysine 9 histone 3 effects energy balance, we focused on the role of the enzyme KDM4D, as it specifically demethylates H3K9 and has been shown to be involved in obesity." (PMID 36817590, 2023). "We propose that the action of KDM4D through the demethylation of H3K9 is critical in maintaining a stable epigenetic landscape of the AgRP promoter, and may offer a target to develop new treatments for obesity." (PMID 36817590, 2023). "The novel potential role of KDM4D in the onset and reversal of obesity has not yet been elucidated." (PMID 36817590, 2023).
renal carcinoma (1 paper, 2021). A carcinoma arising from the epithelium of the renal parenchyma or the renal pelvis. "As a result, we found that inhibiting KDM4D can restrain the ability of clonal formation, migration, and invasion of renal cancer cells." (PMID 34667158, 2021). "All in all, the research discusses that KDM4D predicts a worse prognosis and regulates the proliferation, migration, and angiogenesis of renal cancer." (PMID 34667158, 2021). "To investigate the effect of KDM4D inhibition on the proliferation and apoptosis of renal cancer cells, we performed flow cytometry to detect apoptotic cells and CCK8 assays to assess the proliferation activity." (PMID 34667158, 2021). "To further verify our conjecture, we treated the renal cancer cell lines Caki-1 and 786-O with KDM4D inhibitors, and then performed a series of experiments." (PMID 34667158, 2021). "To clarify the detailed mechanism of KDM4D in renal cancer cell development, we performed RNA-seq analysis for 786-O cells treated with KDM4D inhibitor or not." (PMID 34667158, 2021).
cancer (14 papers, 2012 to 2025). A tumor composed of atypical neoplastic, often pleomorphic cells that invade other tissues. "In gastrointestinal tumors, KDM4D promotes cancer progression by directly interacting with hypoxia-inducible factor (HIF) 1β gene and activating its expression via H3K9me3 demethylation of the vascular endothelial growth factor A promoter region." (PMID 34778065, 2021). "Histone demethylase KDM4D has been reported to be responsible for development of a variety of cancers." (PMID 34667158, 2021). "KDM3A and KDM3B are well known to be tightly related to cancer, whereas KDM3C and KDM4D are relatively unstudied in cancer development." (PMID 32354028, 2020). "Indeed, we noted a robust correlation in the expression of KDM4A, KDM4B, KDM4C and KDM4D across all tumour samples in the TCGA pan‐cancer database." (PMID 38390756, 2024). "JIB-04 is a pan-selective inhibitor of various proteins in the KDM family, with a high selectivity for KDM4D and has been used both in vitro to inhibit cancer cell activity and in vivo to inhibit different types of cancer growths and it increases survival rates in mice." (PMID 36817590, 2023). "Considering the extensive involvement of KDM4D in different cancers, we suppose that KDM4D may also act as a cancer driver gene in ccRCC." (PMID 34667158, 2021). "Histone lysine demethylase 4D (KDM4D or JMJD2D) is highly expressed in colon and liver tumors, where it promotes cancer progression; however, the role of JMJD2D in CSCs remains unclear." (PMID 33434575, 2021). "The role of KDM4D in cancer is relatively less studied than that of other KDM4s." (PMID 34778065, 2021). "This indicates that post-translational epigenetic alterations are possibly involved in ccRCC progression and KDM4D may be a cancer driver gene of ccRCC." (PMID 34667158, 2021). "Therefore, KDM4D could be exploited as a prognostic marker or a target for anti-cancer therapy, but its specificity and practicality require rigorous preclinical testing in the future." (PMID 34667158, 2021). "In TCGA pan‐cancer database, tumour tissues generally exhibited higher expression levels of KDM4A, KDM4B and KDM4D compared to normal tissues." (PMID 38390756, 2024).
tumor (14 papers, 2012 to 2025). "Targeting HMGB1 (Glycyrrhizin) could remarkably suppress ESCC tumor growth in vitro and in vivo, especially in KDM4D-deficient cells." (PMID 34820329, 2021). "In line with the in vitro results, we also observed that Glycyrrhizin could effectively suppressed the elevated in vivo tumor growth induced by KDM4D deficiency, as indicated by the tumor volumes and weight." (PMID 34820329, 2021). "KDM4D deficiency significantly enhanced tumor growth, migration and stemness." (PMID 34820329, 2021). "RNA-sequencing (RNA-seq) analysis of 566 samples (44 normal and 522 tumour) suggested that LEF1, KDM4A, and KDM4D were expressed at higher levels in tumour tissues than in normal tissues, whereas KDM4B was expressed at lower levels in tumour tissues." (PMID 37553362, 2023). "Considering that tumor stemness correlated tightly with drug resistance, we treated the ESCA cells with cisplatin and observed that KDM4D loss rendered cells more resistant to chemotherapy-induced apoptosis." (PMID 34820329, 2021). "Mechanistically, KDM4D/SYVN1/HMGB1 axis modulates the tumor growth, migration and self-renewal features via promoting accumulations of HMGB1." (PMID 34820329, 2021). "Lastly, we integrated the KDM4D expression data with clinical information and confirmed that KDM4D correlated negatively with hazard factors, including T stages, N stages and tumor grades." (PMID 34820329, 2021). "The overexpression of KDM4D in gastrointestinal stromal tumor tissues activates the HIF1β gene promoter activity by decreasing the binding of H3K36me3 to the HIF1β gene promoter and induces tumor angiogenesis via the HIF1β/VEGFA signaling pathway." (PMID 34715919, 2021). "KDM4D expressed lowly in tumor samples relative to normal tissues and low KDM4D correlated with hazard clinical characteristics and poor survival outcomes." (PMID 34820329, 2021). "The effects of KDM4D on tumor angiogenesis in vivo were assessed by conducting xenograft tumor assays in nude mice." (PMID 34667158, 2021). "Results showed that inhibition of KDM4D can indeed impede the growth of xenograft and tumor angiogenesis." (PMID 34667158, 2021). "Epigenome screening and low-throughput validations highlighted that KDM4D is a tumor suppressor in ESCC." (PMID 34820329, 2021). "Here, we screened the prognostic epigenetic regulators in TCGA-ESCC and identified KDM4D as a tumor suppressor via low-throughput validations." (PMID 34820329, 2021). "Third, we demonstrated that KDM4D is required for tumour angiogenesis via regulating VEGFA secretion." (PMID 30060750, 2018). "In contrast, silencing KDM4D reduced cell proliferation, migration, invasion and tumour angiogenesis." (PMID 30060750, 2018). "To further observe the effect of KDM4D on tumor angiogenesis, we performed tube formation assays." (PMID 34667158, 2021). "First of all, we found KDM4D expressed lowly in tumor samples relative to normal tissues." (PMID 34820329, 2021). "Taken together, our data indicated that KDM4D is a tumor suppressor and KDM4D inhibition could promote ESCC proliferation, migration, stemness features and resistance to chemotherapy." (PMID 34820329, 2021). "In the present study, we evaluated the role of KDM4D in tumour angiogenesis." (PMID 30060750, 2018). "Furthermore, we found that HIF1β overexpression reverses the attenuated tumour migration, invasion and angiogenesis mediated by silenced KDM4D." (PMID 30060750, 2018). "Furthermore, we demonstrated that KDM4D directly interacted with the HIF1β gene promoter and regulated its activity, promoting tumour angiogenesis and GIST progression both in vitro and in vivo." (PMID 30060750, 2018). "Besides, low KDM4D correlated with advanced tumor grades, as evidenced by the IHC graphs." (PMID 34820329, 2021). "Previous studies have already found that KDM4D may function as an oncogene that modulates multiple cellular processes, including transcriptional regulation, cell differentiation, stem cell renewal, and tumor metastasis." (PMID 34820329, 2021).
tumor (continued). "Importantly, immunohistochemistry (IHC) assay results also demonstrated that CD31 expression was significantly upregulated in the KDM4D group compared with the control vector group, indicating that tumour microvessel density was strongly increased in the KDM4D group." (PMID 30060750, 2018). "Thus, we further evaluate the function of KDM4D in tumour angiogenesis." (PMID 30060750, 2018). "Further, KDM4D overexpression strongly promotes GIST cell proliferation, migration, invasion and tumour angiogenesis." (PMID 30060750, 2018). "Additionally, KDM4D plays a role in mediating inflammatory responses triggered by cytokines such as TNF-α, potentially influencing tumorigenesis within the tumor microenvironment and immune cells." (PMID 39620228, 2024). "KDM4D, which is distinct from other KDM4 proteins due to its lack of PHD and Tudor domains, also acts as a coactivator of the androgen receptor, similar to KDM4A and KDM4C, thereby promoting tumor progression." (PMID 39620228, 2024). "In this study, we identified that KDM4D/SYVN1 axis could modulate the post-transcriptional regulation of HMGB1, providing novel insights on HMGB1 accumulations in tumor." (PMID 34820329, 2021). "Finally, we disclosed that KDM4D directly interacts with JAG1 promoter and advances tumor angiogenesis by upregulating VEGFR-3 and antagonizing notch signaling." (PMID 34667158, 2021).
KDM4D also shares sentences with these, for which no sentence is quoted: colorectal cancer (6 papers); colitis (5); colon cancer (3); infection (3); acute myeloid leukemia (2); colorectal tumor (2); esophageal squamous cell carcinoma (2); osteosarcoma (2); adenocarcinoma (1); Anxiety (1); depression (1); fibrosis (1); inflammatory bowel disease (1); lung adenocarcinoma (1); mood disorder (1); periodontitis (1); prostate (1); prostate carcinoma (1); prostate tumors (1); psychiatric disorder (1); Sepsis (1); uterine corpus endometrioid carcinoma (1); viral infection (1).